ANO1 (anoctamin 1)
Diseases named in the same sentence as ANO1 in open-access papers (continued):
Sharing a sentence is not in itself a finding about the gene and the disease.
lung carcinoma (33 papers, 2015 to 2025). "For instance, ANO1 knockdown with small hairpin RNAs (shRNAs) inhibited the migration, proliferation, and invasion of human lung cancer cell, and silencing ANO1 in vivo reduced tumor growth." (PMID 38892219, 2024). "For instance, ANO1 knockdown with small hairpin RNAs (shRNAs) inhibited the proliferation, migration, and invasion of human lung cancer cells and the tumor growth was significantly reduced by ANO1 silencing in nude mice." (PMID 36674697, 2023). "Anoctamin-1 is upregulated in many tumors, including prostate, breast, colorectal, and lung cancers." (PMID 37749499, 2023). "In this study, we have demonstrated that ANO1 is highly overexpressed in several lung cancer cell lines and human adenocarcinoma tissue samples." (PMID 26305547, 2015). "To evaluate the biological role of ANO1 in lung cancer cell proliferation, we used shRNAs to knockdown the expression of ANO1 in different cell lines." (PMID 26305547, 2015). "In NCI-H520 lung cancer cells, the wound-healing in ANO1 knockdown group was only about 29.1% at 24 h and 27.6% at 48 h as compared with the scrambled shRNA control group." (PMID 26305547, 2015). "Transfecting GLC82 lung cancer cells with ANO1 shRNA inhibited the wound filling about 66.8% at 24 h, 67.5% at 48 h and 74.3% at 72 h, as compared with scrambled shRNA." (PMID 26305547, 2015). "In this study, we show that inhibition of calcium-activated chloride channel ANO1/TMEM16A suppresses tumor growth and invasion in human lung cancer." (PMID 26305547, 2015). "Using immunohistochemistry, our initial finding revealed that ANO1 was overexpressed in human lung cancer tissues especially in adenocarcinoma." (PMID 26305547, 2015). "In summary, we have shown in this study that ANO1 is overexpressed in human lung adenocarcinoma tissues and upregulated in lung cancer cell lines." (PMID 26305547, 2015). "Knockdown of ANO1 expression by short hairpin RNA inhibited cellular proliferation, migration and invasion in lung cancer cells GLC82 and NCI-H520." (PMID 26305547, 2015). "In addition, CEP also suppressed endogenous ANO1 currents, significantly inhibited cell proliferation and migration, and induced death in lung cancer cells." (PMID 36192752, 2022). "In addition, ANO1 upregulated in cancer cells such as pancreatic cancer, lung cancer, and gastrointestinal stromal tumor cells was reduced by T16Ainh-A01." (PMID 34281197, 2021). "Notably, the ANO1 expression level in PC9 lung cancer cells was twice as high as that in the protein sample derived from FRT cells stably overexpressing ANO1." (PMID 34281152, 2021). "Our findings provide evidence that membrane ANO1 protein may serve as a potential biomarker and target for diagnosis and therapy of lung cancer." (PMID 26305547, 2015). "Therefore, it is likely that ANO1 overexpression in lung cancer results in activation of oncogenic signaling pathways that are partially shared in the pathogenesis of epithelial tumors." (PMID 26305547, 2015). "Taken together, our findings provide evidence that ANO1 overexpression contributes to tumor growth and invasion of lung cancer; and suppressing ANO1 overexpression may have therapeutic potential in lung cancer therapy." (PMID 26305547, 2015). "ANO1 upregulation was confirmed in different human lung cancer cell lines." (PMID 26305547, 2015). "ANO1 is upregulated in different human lung cancer cell lines." (PMID 26305547, 2015). "Correlation between ANO1 expression and lung cancer genesis from human tissue samples." (PMID 26305547, 2015). "In this study, we found that CaCC ANO1 is highly upregulated in human lung cancer tissues." (PMID 26305547, 2015). "Among the pathological stimuli, ANO1 expression was transiently induced by the bacterial toxin lipopolysaccharide (LPS) in human lung adenocarcinoma A549 cells, in cultured mouse lung cancer cell line LA795, and in mouse alveolar epithelial cells in vivo after intraperitoneal injection of LPS." (PMID 33250781, 2020).
lung carcinoma (continued). "Therefore, pharmacological inhibition of upregulated ANO1 may provide a strategy and therapeutic potential for treatment of lung cancer or other epithelial cancers." (PMID 26305547, 2015). "To measure the expression level of ANO1 in various lung cancer cell lines, we confirmed endogenous ANO1 protein expression levels in FRT cells, FRT cells stably expressing ANO1, and various lung cancer cell lines." (PMID 34281152, 2021). "However, whether ANO1/TMEM16A plays a role in tumor genesis of lung cancer remains unknown." (PMID 26305547, 2015). "As a natural product with no hepatotoxicity or adverse cardiac effects, vitexicarpin holds promise as a valuable pharmacological tool in ANO1 inhibitor research and as a potential therapeutic for CRC and lung cancers, particularly in cases of resistance to existing anticancer drugs." (PMID 40520165, 2025). "In addition, recent evidence indicated ANO1 blockade can enhance the anti-tumor effect of cisplatin in HNSCC and lung cancer." (PMID 40396170, 2025). "ANO1 overexpression and function have been reported in a variety of carcinoma cells; however, the expression and function of ANO1 in lung cancer cells has not been comprehensively studied." (PMID 34281152, 2021). "Interestingly, LPS increased currents in whole-cell patch recordings in cultured mouse lung cancer cell line LA795, and this was reduced by ANO1 knockdown; however, the role of calcium in these currents was not demonstrated." (PMID 33250781, 2020). "Moreover, the Ca2+-activated Cl− channel ANO1 (anoctamin-1, transmembrane member 16A, TMEM16A) is overexpressed in lung cancer cells where it promotes invasion." (PMID 27618016, 2016). "To confirm whether this effect of the pharmacological inhibition of ANO1 was also applicable to lung cancer cells, we selected H1975 cells that did not express ANO1 and PC9 cells highly expressing ANO1." (PMID 34281152, 2021).
Hypertension (32 papers, 2013 to 2025). The presence of chronic increased pressure in the systemic arterial system. "The mechanisms underlying the involvement of ANO1 in the initiation and progression of different types of hypertension are intricate and controversial." (PMID 41210337, 2025). "Numerous studies concluded that ANO1 was negatively associated with cerebrovascular remodelling during hypertension." (PMID 41210337, 2025). "A growing body of literature has investigated the application of ANO1 inhibitors in the cardiocerebral vascular system, especially anti-hypertension or anti-cardiac diseases." (PMID 41210337, 2025). "This reciprocal regulation between ANO1 and humoral factors underscores a potential therapeutic avenue for managing hypertension." (PMID 40356890, 2025). "The multifaceted role of ANO1 in both smooth muscle and endothelial cells highlights its potential as a promising therapeutic target in hypertension and vascular diseases." (PMID 40356890, 2025). "Accumulating evidence has proven that ANO1 plays an important role in the pathophysiology of hypertension, not only in vascular contraction but also in vascular remodelling, including changes in endothelial and VSMC function." (PMID 41210337, 2025). "Next, we elaborate on the role of ANO1 in different types of hypertension, including systemic hypertension, pulmonary arterial hypertension, and portal hypertension." (PMID 41210337, 2025). "This Ang II-induced ANO1 overexpression increases VSMCs sensitivity to additional agonists, thus exacerbating hypertension." (PMID 40356890, 2025). "The Ca2+-activated chloride channel named TMEM16A/Ano1 is involved in several pathologies as hypertension, stroke and cancer and was expressed in several cell types in mammalians, including smooth muscle and epithelial cells, as reviewed recently." (PMID 36356031, 2022). "Consistent with this role, ANO1 has been found to be upregulated in experimental models with circulatory abnormalities, for example, pulmonary and essential hypertension." (PMID 33245843, 2020). "Aberrant expression or dysfunction of ANO1 is associated with several cardiocerebral vascular diseases, including myocardial ischaemia/reperfusion injury (MIRI), arrhythmias, cardiac fibrosis, hypertension, and stroke." (PMID 41210337, 2025). "For all laboratory forms and models of hypertension, a complete investigation of the effects of blocking ANO1 to reduce BP is needed, as this may have unfavourable outcomes in cerebral and portal microcirculation." (PMID 41210337, 2025). "Genetic diversity in ANO1 has been statistically associated with hypertension in humans, especially in males, although this has not been demonstrated by genome-wide sequencing studies." (PMID 41210337, 2025). "Thus, ANO1 expression appears to be highly context-dependent, shaped by the predominant etiological factors and the stage of hypertension development." (PMID 41210337, 2025). "This is supported by the finding that ANO1 knockout mice remain susceptible to salt-induced hypertension, underscoring that ANO1 is not part of the primary, kidney-dependent long-term control system." (PMID 41210337, 2025). "Similarly, in spontaneous hypertensive rats (SHR), ANO1 overexpression stimulates VSMCs proliferation and vascular remodeling and enhances Ca2+ influx, contributing to increased peripheral resistance and hypertension." (PMID 40356890, 2025). "Thus, ANO1 is strongly upregulated in pulmonary and primary hypertension but reduced in secondary systemic hypertension." (PMID 33245843, 2020). "Moverover, excess expression of ANO1 impaired endothelial function, possibly via the generation of reactive oxygen species and the reduction of nitric oxide, triggering vascular remodelling and ensued numerous cardiovascular diseases (different types of hypertension, stroke, etc.)." (PMID 41210337, 2025).
Hypertension (continued). "Therefore, this review provides an overview of ANO1, including its structure, distribution, and activation mechanism, and highlights the current knowledge of ANO1 in the pathophysiological process of heart diseases, hypertension, and stroke." (PMID 41210337, 2025). "As a calcium-activated chloride channel, ANO1 can increase vascular smooth muscle contractility and can be a promising target for treating hypertension." (PMID 38352864, 2024). "Particular emphasis is given to the roles of Ca2+-activated Cl− channel transmembrane membrane 16A (TMEM16A; also known as Ano1) and Na+–K+–2Cl− cotransporter 1 (NKCC1) in the increased vascular contractility during hypertension." (PMID 36140417, 2022). "Numerous studies have shown that ANO1 is involved in several pathological processes in the cardiocerebral vascular system: myocardial ischaemia/reperfusion injury (MIRI), arrhythmia, myocardial fibrosis, hypertension and stroke." (PMID 41210337, 2025). "By contrast, hypertension in the acute AngII infusion model is primarily driven by the potent vasoconstrictor AngII, and the observed downregulation of ANO1 may act as a negative feedback response to mitigate excessive vasoconstriction and calcium overload." (PMID 41210337, 2025).
pancreatic cancer (29 papers, 2012 to 2025). "It inhibits ANO1 channel activity and has antitumour effects on prostate and pancreatic cancer cells in a dose-dependent manner." (PMID 40396170, 2025). "The results revealed that high levels of ANO1 and KRAS were associated with activating key genes involved in lipid metabolism like HMGCS1, indicating that ANO1 regulated basic metabolic processes that occured in pancreatic cancer cells." (PMID 40396170, 2025). "Sixty-one percent of pancreatic cancer tissues have high levels of ANO1 expression, and patients with ANO1-positive tumours have worse overall survival than patients who do not." (PMID 40396170, 2025). "Univariate and multivariate analysis of overall survival according to ANO1 expression in patients with pancreatic cancer." (PMID 38352864, 2024). "Upregulation of TNF-α signaling was reported to be involved in inducing apoptosis by ANO1 downregulation in PC-3 pancreatic cancer cells." (PMID 36674697, 2023). "Overexpression of ANO1 promotes pancreatic cancer cell migration via the ligand-dependent EGFR signaling pathway." (PMID 33901011, 2021). "Recent evidence suggests that ANO1 is a potential therapeutic target for cancers such as prostate, oral, breast, and pancreatic cancer." (PMID 32899792, 2020). "For example, the receptor tyrosine kinase (RTK) ligand EGF stimulated a transient calcium response and activated CaCC in the pancreatic cancer cell line AsPC-1, which was inhibited by ANO1 knockdown." (PMID 33250781, 2020). "ANO1 is also required for EGF-induced store-operated calcium entry (SOCE) in pancreatic cancer cells; however, in both latter studies, the precise mechanism by which ANO controls Ca2+ signaling was not determined." (PMID 33250781, 2020). "In HNSCC cell lines BHY, HEp-2, SCC-25 and some pancreatic cancer cell lines, ANO1 overexpression or knockdown affects cell migration rather than proliferation." (PMID 27732935, 2016). "Pharmacological inhibition of ANO1 by T16Ainh-A01, a selective ANO1 inhibitor, reduced proliferation of interstitial cells of Cajal (ICC) and CFPAC-1 pancreatic cancer cells expressing endogenous ANO1." (PMID 26196390, 2015). "In the present study, we provided compelling evidence that ANO1 is functionally overexpressed in human pancreatic cancer cell lines and that it carries the major component of CaCC currents in these cells." (PMID 25163766, 2015). "ANO1, a calcium-activated chloride channel, is a biomarker for poor prognosis in pancreatic cancer." (PMID 33901011, 2021). "A novel 14-gene signature comprising CCDC148, SH3RF2, CACNA1D, POLD3, PARP1, AP1M2, C4orf19, ANO1, VGLL1, SCEL, INPP4B, NET1, INSIG2 and BVES and a corresponding risk score formula were established for pancreatic cancer risk stratification and prognosis prediction." (PMID 33731794, 2021). "Chloride channel blockers inhibited proliferation of ANO1-expressing pancreatic cancer cells." (PMID 29416639, 2018). "In addition, ANO1 inhibitors inhibit cell proliferation of prostate and pancreatic cancer cells, and reduce mucus production in primary human airway epithelium and contraction of airway smooth muscle." (PMID 27219012, 2016). "Similarly, the selective Ano1 inhibitor T16A(inh)-A01, which inhibits CaCC currents, also reduces proliferation of interstitial cells of Cajal and a pancreatic cancer cell line CFPAC-1." (PMID 24663380, 2014). "Moreover, bioinformatic analysis of the TCGA dataset revealed that ANO1 may induce an immunosuppressive tumor microenvironment in pancreatic cancer in a paracrine manner." (PMID 38352864, 2024). "ANO1 (TMEM16A) is a recently identified Ca(2 +)-activated Cl(−) channel (CaCC) that is upregulated in pancreatic ductal adenocarcinoma (PDAC), it is also a gene up-regulated in pancreatic cancer samples." (PMID 37170188, 2023). "ANO1, AHNAK2, and ADAM9 were eventually identified as feature genes of pancreatic cancer, helping to diagnose and predict prognosis." (PMID 37170188, 2023).
pancreatic cancer (continued). "The results showed that only three feature genes—ANO1, AHNAK2, and ADAM9, were significantly associated with prognosis in all three analyses (p < 0.05), which means that these three feature genes may act as molecular markers for predicting the prognosis of pancreatic cancer patients." (PMID 37170188, 2023). "In this study, a four-gene prognostic signature that included SPINK1, ANO1, DSG3, and GIMAP1 in patients with pancreatic cancer were identified." (PMID 33901011, 2021). "Application of Cl channel blockers (DIDS, Niflumic acid or Tamoxifen) decreased the proliferation of ANO1-expressing cells, ICC, and CFPAC-1 (pancreatic cancer-derived cell line) but had less effect on ANO1 ICC cells." (PMID 24639373, 2014). "Similar results were obtained in pancreatic cancer cells (CF-PAC1), which also express Ano1." (PMID 22912841, 2012). "Thus, ANO1 inhibitors may be useful for the treatment of BPH, prostate and pancreatic cancer, and inflammatory airway diseases." (PMID 27219012, 2016).
esophageal squamous cell carcinoma (27 papers, 2012 to 2025). Esophageal squamous cell carcinoma (ESCC) is a type of esophageal carcinoma (EC) that can affect any part of the esophagus, but is usually located in the upper or middle third. "For example, in esophageal squamous cell carcinoma, both mRNA and protein levels of ANO1 were upregulated and correlated with an unfavorable clinical prognosis." (PMID 38352864, 2024). "In esophageal squamous cell carcinoma, ANO1 regulates the tumor growth factor-B signaling pathway and promotes proliferation, migration, and invasion." (PMID 38352864, 2024). "In one study, ANO1-expressing esophageal squamous cell carcinoma cells activated NFκB signaling in fibroblasts, stimulating CCL1 production, and subsequently enhance invasion." (PMID 38352864, 2024). "Anoctamin 1 (ANO1) has been found to be overexpressed in esophageal squamous cell carcinoma (ESCC) in our previous study." (PMID 27016410, 2016). "In metastatic esophageal squamous cell carcinoma (ESCC), tumor cells upregulate anoctamin-1 (ANO1), which drives both cell-intrinsic and cell-extrinsic mechanisms to alter cholesterol metabolism and stimulate fibroblast activity." (PMID 40270603, 2025). "The inhibition of TRPV2 by tranilast; inhibition of ANO1 by T16Ainh-A01, digallic acid, and tannic acids; and the inhibition of voltage-gated sodium channels by valproic acid were reported as potential targeted therapeutic agents in esophageal squamous cell carcinoma." (PMID 37529379, 2023). "Ano1 expression was more frequent (>10%) in HNSCC, GISTs (100%), adenocarcinomas and squamous cell carcinomas of the esophagus (both 13%) and adenocarcinomas of the gall bladder (11%)." (PMID 22912841, 2012).